RN7SKP124 (RN7SK pseudogene 124)
Gene: Miscellaneous RNA gene on chromosome 3 (139,584,105 to 139,584,445, reverse strand). Ensembl gene ENSG00000201600.
Homologues: Orthologues: chimpanzee 7SK (99% identical). Paralogues in human: RN7SKP203 (73% identical), RN7SKP71 (72% identical), 7SK (72% identical), RN7SKP133 (71% identical), RN7SKP225 (71% identical), RN7SKP90 (71% identical), RN7SKP180 (70% identical), RN7SKP79 (70% identical), RN7SKP255 (70% identical), RN7SKP9 (70% identical), RN7SKP78 (70% identical), RN7SKP86 (70% identical), and 283 more.